C11orf68 (chromosome 11 open reading frame 68)
Synonyms: BLES03; P5326
Tractability: Small molecule: it has a high-quality binding pocket. PROTAC: ubiquitination databases record sites on it; its protein half-life has been measured.
Gene: Protein-coding gene on chromosome 11 (65,916,810 to 65,919,062, reverse strand). Ensembl gene ENSG00000175573.
Subcellular location (Human Protein Atlas): Nucleoli; Nucleoplasm; Nucleoli rim
Gene Ontology:
Molecular function: protein binding; RNA binding
Genetic constraint (gnomAD): Loss-of-function variants: 3 observed, 2.97 expected, observed/expected ratio (o/e) 1.01, 90% interval 0.43 to 1.86. That is too few expected variants to judge how well the gene tolerates losing a copy. Missense variants: 422 observed, 385.69 expected, observed/expected ratio (o/e) 1.09, 90% interval 1.01 to 1.19. Synonymous variants: 186 observed, 163.4 expected, observed/expected ratio (o/e) 1.14, 90% interval 1.01 to 1.29.
Homologues: Orthologues: chimpanzee C11H11orf68 (99% identical), pig C11orf68 (96% identical), dog C11orf68 (95% identical), rat Bles03 (95% identical), guinea pig C11orf68 (94% identical), mouse AI837181 (94% identical), rabbit C11orf68 (92% identical), macaque C14H11orf68 (88% identical), zebrafish C7H11orf68 (47% identical), tropical clawed frog c4h11orf68 (46% identical).
Diseases named in the same sentence as C11orf68 in open-access papers:
C11orf68 is named in the same sentence as 9 diseases in open-access papers, as found by Europe PMC text mining. Sharing a sentence is not in itself a finding about the gene and the disease. The quoted sentences say what the papers report.
leiomyosarcoma (1 paper, 2015). An uncommon, aggressive malignant smooth muscle neoplasm, usually occurring in post-menopausal women. "We did not detect any expression of C11orf68 in normal prostate tissues (n = 7) and low grade malignant leiomyosarcoma tissues (n = 9), however 22 out of 80 prostate adenocarcinoma tissues were positively stained." (PMID 26427334, 2015).
lobular carcinomas (1 paper, 2015). "Interestingly, the expression of C11orf68 was higher in invasive ductal and lobular carcinomas compared to medullary carcinoma (n = 9) (p < 0.05), which is known to be the only carcinoma associated with BRCA1 mutation." (PMID 26427334, 2015).
prostate carcinoma (1 paper, 2015). A carcinoma that arises from epithelial cells of the prostate gland. "Depletion of C11orf68 resulted in inhibition of invasiveness in breast MDA-MB-231 and liver SKHep1 cell lines but not in PC3 prostate cancer cells." (PMID 26427334, 2015).
cancer (2 papers, 2014 to 2015). A tumor composed of atypical neoplastic, often pleomorphic cells that invade other tissues. "The other genes that were examined, TMEM156 and C11orf68, to our knowledge were never shown to have biochemical or cellular role that could be linked to cancer." (PMID 26427334, 2015). "To provide a proof of principle that the list of genes that are commonly hypomethylated and induced in 3 invasive cancer cell lines could serve as a source for discovery of new genes involved in invasiveness, we picked four genes, C11orf68, G0S2, SHISA2 and TMEM156." (PMID 26427334, 2015).
C11orf68 also shares sentences with these, for which no sentence is quoted: tumor (4 papers); basophilic leukemia (1); medullary carcinoma (1); ovarian carcinoma (1); prostate adenocarcinoma (1).